AR (androgen receptor)
Diseases named in the same sentence as AR in open-access papers (continued):
Sharing a sentence is not in itself a finding about the gene and the disease.
breast carcinoma (continued). "Our analysis of a breast cancer dataset finds that the positive feedback loops across 7 genes, AR, ESR1, MYC, E2F2, PGR, BCL2 and CCND1 are conserved across the basal/triple negative subtypes in multiple datasets that could potentially explain the aggressive nature of this cancer subtype." (PMID 23368093, 2013). "The AR antagonizes the mitogenic activity of the estrogen receptor suggesting that AR may oppose ERα activity during the early stages of MMTV-NeuNT driven tumorigenesis and AR loss leads to the accelerated onset of mammary tumors." (PMID 23593223, 2013). "Third, approximately 40% to 50% of ERα-positive breast cancers treated with conventional hormone therapies such as tamoxifen or aromatase inhibitors (AIs) will recur with drug-resistant disease, and AR-directed therapies may still be efficacious in this patient population." (PMID 22321971, 2012). "This suggests that the GASC1 and the AR might be functionally connected also in breast cancers." (PMID 23148692, 2012). "Thus, despite the past experience of and caveats about targeting AR for breast cancer, developing novel therapies that target AR could have a significant influence on the treatment of this disease." (PMID 22321971, 2012). "However, there are several reasons why AR remains a potential target for breast cancer therapy." (PMID 22321971, 2012). "Mutations in the AR gene have been reported in male patients with breast cancer, but again no causal association could be demonstrated." (PMID 23273269, 2012). "However, literature data report AR expression in 34 to 95% of male breast cancer with no clear association with its prognosis." (PMID 23273269, 2012). "The main finding of the present study was that adjuvant therapy with TAM, but not with AI, was significantly associated with longer breast cancer-free survival in patients carrying certain AR diplotype variants (group B) compared with patients not treated with TAM." (PMID 22033271, 2011). "It is believed that knowledge of the receptor status of all three receptors (ER, PR, AR) may identify more accurately those patients with breast cancer who are most likely to respond to endocrine treatment (Brentani 1986, Langer 1990, Kuenen-Boumeester 1992, Isola 1993, Collett 1996)." (PMID 20831839, 2010). "Thus, the «group query» genes ERBB2, ESR1, CEACAM5 and AR are well known markers of breast cancer." (PMID 20158879, 2010). "However, AR expression was strongly correlated with ER in a series of 842 breast carcinomas." (PMID 19405945, 2009). "In a prior report we found an increase in AR expression in the transition from pure DCIS to DCIS adjacent to the invasive component of breast carcinoma, which led us to consider that there could be a relationship between both AR and MMPs/TIMPs expression in breast carcinoma." (PMID 18507821, 2008). "This experimental model could be used to screen for compounds that can increase breast cancer progression because of their estrogenic potential, their antiandrogenic capacity, or a combination of both since many environmental estrogens are also AR antagonists." (PMID 18275596, 2008). "However, AR expression was not related with the occurrence of distant metastases, but instead associated with a longer overall survival in breast cancer patients." (PMID 18507821, 2008). "Because the ER and the AR belong to the steroid receptor superfamily, we sought to determine whether these pyranocoumarin compounds exerted similar activities against ER expression and function in breast cancer cells." (PMID 17986353, 2007). "Thus, the expression and activation of AR may play an important role in the development of breast cancers and response to hormone therapies." (PMID 16457685, 2005).
breast carcinoma (continued). "In this study, we aimed to investigate the effects of androgen receptor (AR) expression, as well as the AR/ER and AR/PR ratios, on responses to CDK4/6 inhibitor treatment and progression-free survival (PFS) in breast cancer patients." (PMID 40870508, 2025). "Recent evidence has strengthened its role as an emerging biomarker in breast cancer, particularly in TNBC, where AR expression contributes to a distinct molecular phenotype known as the luminal androgen receptor (LAR) subtype." (PMID 41516015, 2025). "ZFHX3 loss promotes ESR1-mediated cell proliferation in ESR1-positive breast cancer cells by upregulating breast cancer stem cells and MYC transcription, and similar findings have been reported in androgen receptor-positive prostate cancer." (PMID 41413856, 2025). "Prior studies on similar analogs, including compounds #7 and #11, showed clear activity against AR/AR-SVs in PCa, Wnt-ß-catenin, mTORC1, and STAT3 in ovarian cancer and NF-κB in breast cancer." (PMID 40805231, 2025). "Key signaling pathways affected by miR‐21 include EMT, androgen receptor (AR) signaling, estrogen receptor (ER) signaling, RAS/MAPK, RTK, and mTOR/TSC pathways, all of which are vital in breast cancer progression." (PMID 40567015, 2025). "For this, we used various human breast cancer cell lines, including MCF7 (HR+), SKBR3 (HER2-enriched), MDA-MB-453 (TNBC- luminal/androgen receptor (LAR)), and MDA-MB-231 (TNBC-mesenchymal-claudin low)." (PMID 40157909, 2025). "In the human ER-breast cancer cell line MDA-MB-453, 5α-5-dihydrotestosterone (DHT) significantly increased cell growth, which was attenuated by cotreating with the AR antagonist bicalutamide." (PMID 40023399, 2025). "Preclinical studies indicate that AR upregulates the expression of the tumor suppressor gene PTEN, thus mediating androgen-induced growth inhibition and apoptosis in breast cancer cells." (PMID 40150035, 2025). "AR also plays an important role in breast cancer, especially TNBC, and there is accumulating evidence that AR has the potential to be a therapeutic target for TNBC." (PMID 40118451, 2025). "The aberrant activity of the Ras/MAPK pathway has been identified as pivotal in the initiation and progression of breast cancer, miR‐21's targeting of key activators within this pathway, including ABCB1, AR, CDK6, CSF1, EREG, MKDR, among others." (PMID 40567015, 2025). "Prior research in multiple ER-positive breast cancer cell lines has shown that FOXA1, functioning as a pioneering transcription factor, aids in opening chromatin and then attracting AR or ER to nearby promoter regions of UGT2B15 genes." (PMID 39856707, 2025). "This highlights the potential for AR and TAN expression patterns to refine patient stratification across breast cancer subtypes." (PMID 40734715, 2025). "In the literature, the AR/ER ratio has been investigated to evaluate the role of AR, and it has been identified as an independent predictor of overall survival (OS) and disease-free survival (DFS) in breast cancer patients." (PMID 40870508, 2025). "We then analyzed the mRNA expression levels of AR and SOX2-OT in the The Cancer Genome Atlas breast cancer patients." (PMID 40118451, 2025). "A phase I trial (NCT03207529) investigated enzalutamide in combination with the alfa-subunit selective PI3K inhibitor alpelisib in patients with AR- and PTEN-positive advanced breast cancer, including TNBC." (PMID 40003864, 2025). "The downregulated genes (ESR1, AR, SPDEF, and FOXA1) participate in hormone receptor signaling and epithelial integrity in breast cancer." (PMID 41462902, 2025).
breast carcinoma (continued). "BQ overexpressed breast cancer cell lines (MCF-7, T-47D, BT-549, MDA-MB-453), showed increased AR activity (ARE-luciferase assay) and demonstrated DOX resistance (EC50 > 10-fold with DHT, p < 0.05), as assessed via cell viability, TUNEL, and comet assays." (PMID 40940753, 2025). "Male sex hormones, including testosterone, have also been reported to influence CXCL12 production and correlation between AR and CXCL12 expression was observed in breast cancer tissue." (PMID 40589738, 2025). "Targeted therapies aimed at modulating androgen receptor activity, such as selective androgen-receptor modulators or androgen-synthesis inhibitors, could represent promising treatment options for patients with hormone receptor-positive breast cancer or for canine mammary tumors." (PMID 40286049, 2025). "The degree of AR and GATA3 co-occupancy following treatment with DHT was also high in the ER- breast cancer cell lines, representing 80% of GATA3 binding sites in MDA-MB-453 and 60% in MFM-223 cells." (PMID 38317241, 2024). "While most breast cancers are driven by estrogen and progesterone receptors, LAR TNBC relies on the androgen receptor for growth and survival." (PMID 39272660, 2024). "Currently, there is an ongoing trial to test enzalutamide plus alpelisib (an α-specific PI3K inhibitor) in AR-positive/PTEN-positive patients with metastatic TNBC or ERα-positive and/or PR-positive/HER2-negative breast cancer (NCT03207529)." (PMID 38339092, 2024). "Mechanistically, activation of AR in ER+ breast cancer cells sequestered essential transcriptional co-activators (p300, SRC-3) away from ER-regulated cell cycle genes to up-regulate AR target genes, including known tumor suppressors." (PMID 38317241, 2024). "The results showed that JAK2, HPGDS, AR and PARP1 had good potential for targeted treatment of breast cancer." (PMID 38872110, 2024). "For instance, in breast cancer (BC), the coexpression of HER2 and AR amplification has an unclear impact on prognosis, which differs from the context of SGCs." (PMID 39582534, 2024). "In breast cancer cases, HDACis can inhibit metastasis and growth through the IL - 6/STAT3 signaling pathway, while AR antagonists can enhance the antitumor effects of PARP inhibitors in AR-positive breast cancer by regulating the DNA damage response." (PMID 38594722, 2024). "However, key factors dictating AR genomic activity in ER+ breast cancers are largely unknown." (PMID 38317241, 2024). "Data presented herein support the concept that androgen-induced AR/GATA3 interactions facilitate the tumor suppressive function of AR in ER+ and ER- breast cancer contexts." (PMID 38317241, 2024). "To determine the effect of NHRs on PCDH19 expression we screened a set of breast cancer cell lines to identify one that expresses ERα, PGR and AR." (PMID 38280856, 2024). "It is widely known that mSDC can express androgen receptor (AR) and harbor HER2 amplifications mimicking features of prostate and breast cancer." (PMID 37041305, 2023). "This study demonstrated in a retrospective Canadian cohort that AR is expressed by IHC in the majority of breast cancer BrM, and that HER2+ BrM most frequently expressed AR, while TNBC BrM least frequently expressed AR." (PMID 37345085, 2023). "Given experimental data have shown cross-talk between AR and HER2 pathways, which can influence the prognosis of HER2 + breast cancer." (PMID 36929229, 2023).
breast carcinoma (continued). "AR was most frequently expressed in BrM from HER2+ breast cancer (n = 21/28 BrM were AR+), followed by HR+/HER2− breast cancer (n = 9/17), and least frequently in TNBC (n = 2/12) (p = 0.003)." (PMID 37345085, 2023). "In our study, AR expression by IHC was expressed (i.e., expression by IHC > 0% using SP107) in 64.9% of breast cancer BrM." (PMID 37345085, 2023). "Our data indicate that, in ER+ breast cancer cells, the expression of the BH-3-only protein BAD is influenced by AR-dependent signaling, since its cellular levels appear to be significantly increased upon androgen administration." (PMID 37686282, 2023). "Mean absolute AR expression was also highest in BrM from HER2+ breast cancer (mean AR expression 53.1%), followed by HR+/HER2− breast cancer (36.5%), and lowest in TNBC (15%) (ANOVA p = 0.023, p = 0.019 for Tukey HSD between HER2+ vs. TNBC)." (PMID 37345085, 2023). "The tumor underwent analysis for the androgen receptor, GCDFP-15, RNA-seq, and whole-genome sequencing (WGS) to identify the breast cancer subtype and to characterize the cancer genome." (PMID 37583932, 2023). "To date, there were few studies on the predictive function of AR in neoadjuvant response of breast cancer, especially in HER2-positive breast cancer and HR-positive breast cancer." (PMID 37099044, 2023). "We reviewed the literature and clinical trials and set 10% as the cut-off value for AR, which predicted the prognosis of HER2+ breast cancer patients with statistical significance in the current study." (PMID 37085500, 2023). "It is apparent that androgens and AR interact with each other and affect the biology of HER2+ breast cancer, which deserves more clinical and translational research." (PMID 37085500, 2023). "Notwithstanding the role of AR in several pathways, its impact from a biological and clinical standpoint is still controversial in HER2+ breast cancer." (PMID 37085500, 2023). "In order to improve ER+ breast cancer treatment, a combination of endocrine therapies with other compounds, such as CDK4/6 inhibitors, mTOR inhibitors, PI3K inhibitors, and AR antagonists, are under investigation." (PMID 37173983, 2023). "KM plots indicate that higher levels of AR and BAD have, individually, a positive impact on the OS and RFS of ER+ breast cancer patients." (PMID 37686282, 2023). "In HR + /HER2- and HR + /HER2 + breast cancer, AR positive patients had a better prognosis, however in TNBC, AR-positive patients have a poor prognosis." (PMID 37099044, 2023). "When considering cell type information, we found that GPC3-IGF1R interactions were most significant between cells expressing luminal androgen receptor (Luminal-AR) within DCIS and mesenchymal breast cancer cells surrounding the DCIS regions." (PMID 38007580, 2023). "In a small cohort of prostate and breast cancer patients, we find high inter-patient and temporal intra-patient variability in the expression of tissue specific markers such as ER, HER2, AR, PSA and PSMA and EpCAM." (PMID 37568766, 2023). "Notably, previous studies found that the prognostic roles of FOXA1 could be affected by other factors, such as androgen receptor (AR) status, and the combined marker of FOXA1 and AR was found as superior predicting marker of the prognosis compared to the single FOXA1 or AR in breast cancer." (PMID 37568077, 2023). "By analyzing the correlation between AR status and pCR after neoadjuvant therapy in different subtypes of breast cancer, we found that only the TNBC pCR rate was correlated with AR expression status (P = 0.006), and AR-negative patients had a higher pCR rate." (PMID 37099044, 2023).
breast carcinoma (continued). "The results showed that AR-positive patients had a good prognosis in HR + /HER2 − and HR + /HER2 + breast cancers." (PMID 37099044, 2023). "In breast cancer cell lines, primary breast tumors, and metastatic breast cancer, SRARP has been shown to be highly co-expressed with AR." (PMID 37602329, 2023). "A study focusing on the interaction between AR and HER2 in breast cancer cell lines indicates that AR signaling regulates direct transcriptional induction of WNT7B and HER3, resulting in activation of the ligand-dependent Wnt and HER2 signaling pathways." (PMID 37085500, 2023). "Although genes that are particularly specified for breast cancer, such as ESR1, PGR, HER2, EGFR, and AR are highly correlated in mRNA-protein expression, nearly 50% of gene expressions are not consistent with their protein levels both in tumors and cell lines." (PMID 37408196, 2023). "This is higher than what was reported in a previous study which demonstrated that AR expression was expressed (i.e., expression by IHC > 0% using AR441) in 35.1% of breast cancer BrM in a similar-sized cohort." (PMID 37345085, 2023). "Approximately 70–90% of luminal breast cancers and 60–70% of HER2-positive breast cancers express AR." (PMID 35207749, 2022). "Since ERα needs a co-regulatory protein SRC-3 to recruit p300 while AR can bind to p300 directly, AR may obtain an advantage in the competition with ERα, resulting in suppression of ER signaling; the activation of AR, therefore, demonstrated an inhibitive effect on ER + ve breast cancer cells." (PMID 35053220, 2022). "Data from GSE104177 showed that RAD140, a selective androgen receptor modulator, induces ACE2 expression in human breast cancer xenografts." (PMID 35012625, 2022). "MCF-7, T-47D and ZR-75-1 are luminal breast cancer lines, SKBR-3 and MDA-MB-453 are ER− but express FOXA1 and AR and are representative of the mApo subtype, with ERBB2-amplification and high expression in SKBR-3 and MDA-MB-453, respectively." (PMID 36358871, 2022). "Although 1% is the current cut off used to define ER and PR positivity in breast cancer according to the latest ASCO/CAP guidelines 27, our institution used an AR positivity cut-off of 10%, like other studies of this nature." (PMID 35711833, 2022). "The previous research suggested that AR correlated to the poor DFS and OS in HER2 + ve/ER-ve breast cancer patients." (PMID 35053220, 2022). "In response to the AR agonist CI-4AS-1, the expression of miR-100 and miR-125 was significantly reduced in MDA-MB-453 breast cancer cells, leading to the increased expression of miR-100 and miR-125 target metalloprotease-13 (MMP13)." (PMID 35163477, 2022). "The results from MTT showed that activation of AR made MCF-7 and ZR-75 tolerant to tamoxifen, suggesting that activation of AR signaling can confer tamoxifen resistance in breast cancer." (PMID 35054486, 2022). "For instance, AR expression is negatively correlated with CD4-positive and CD8-positive T cell infiltration in ERα-positive breast cancers." (PMID 37435447, 2022). "The majority of breast cells and tissues tested concurrently expressed ACK1 and AR suggesting that there is a link between ACK1 and AR.in breast cancer." (PMID 35768871, 2022). "This study compared TCGA miRNA sequencing results from women with QNBC, AR+ TNBC, luminal and Her2+ breast cancers." (PMID 35203574, 2022). "Since AR is expressed in all subtypes of breast cancer, especially TNBC, which lacks a clear target, AR is expected to become a potential target for breast cancer treatment." (PMID 35311116, 2022). "To further understand whether the androgen receptor inhibitor may be attributable to cell cycle changes, we used flow cytometry to evaluate the effect of enzalutamide alone and in combination with ribociclib on the cell cycle profile of breast cancer cell lines." (PMID 36548336, 2022).